PLG (plasminogen)
Diseases named in the same sentence as PLG in open-access papers (continued):
Sharing a sentence is not in itself a finding about the gene and the disease.
atypical hemolytic-uremic syndrome (2 papers, 2016 to 2024). A rare, genetic thrombotic microangiopathy due to dysregulation of the alternative complement pathway and characterized by the triad of hemolytic anemia, thrombocytopenia, and acute renal dysfunction. "The PLG/K19E variant and other relatively abundant variants of concern found in PDI or PDII, viz., R234H and PLG/G693R, have been reported in patients with atypical hemolytic uremic syndrome (AHUS)." (PMID 38984351, 2024). "PLG/G560R, is associated with PDI, atypical hemolytic-uremic syndrome and HAE." (PMID 38984351, 2024).
autoimmune disease (2 papers, 2016 to 2021). A disorder resulting from loss of function or tissue destruction of an organ or multiple organs, arising from humoral or cellular immune responses of the individual to their own tissue constituents. "Although there is no indication that heterozygous carriers are at an increased risk of developing disease, PLG dysregulation could lead to an increased susceptibility to inflammatory and autoimmune diseases." (PMID 27194806, 2016).
Behçet's disease (2 papers, 2022 to 2023). "Similar to Behcet’s disease, endothelial cell plasminogen activation, platelet dysfunction, and fibrin accumulation are the recognized pathogenesis of LV." (PMID 35455298, 2022).
bleeding disorders (2 papers, 2017 to 2026). "Altogether, we identified a novel mechanism by which NS1 might contribute to bleeding disorders, highlighting the relevance of the plasminogen/plasmin system for DENV pathogenesis in humans." (PMID 42054092, 2026). "Prolongation of aPTT and PT, decreased platelets count, plasma fibrinogen level, prothrombin, factor VIII, plasminogen and antithrombin III activities were observed transiently during acute phase of DHF and they characterize hemorrhagic diathesis of DVI severe patients." (PMID 28103832, 2017).
bubonic plague (2 papers, 2016 to 2020). A plague in which the bacteria have infected the lymphatic system. "The Pla protease plays a central role in the invasiveness of the bubonic plague, converting plasminogen to plasmin, which dissolves the fibrin clots surrounding the infected site." (PMID 27014253, 2016). "Therefore, whether Pla cleaves the plasminogen during the bubonic plague, this cleavage can only partially explain the role of Pla in this form of the disease." (PMID 33202679, 2020).
carcinomas of the colon (2 papers, 1995 to 1996). "Here we present the effect of inflammatory cytokines on the plasminogen activation system of eight human colon carcinoma cell lines." (PMID 8826848, 1996).
chronic pancreatitis (2 papers, 2018 to 2019). A chronic inflammatory process causing damage and fibrosis of the pancreatic parenchyma. "A second confirmatory phase on an independent cohort of 131 PDAC patients, 30 chronic pancreatitis patients, and 131 healthy subjects confirmed the PDAC association for MMP7, CCN2, IGFBP2, TSP2, sICAM1, TIMP1, and PLG." (PMID 29941541, 2018). "Moreover, a panel consisting of CCN2, plasminogen (PGL), fibronectin, collagen 4 and CA19.9 was found able to distinguish PDAC from chronic pancreatitis patients." (PMID 30678058, 2019).
co-infection (2 papers, 2022 to 2024). "Whereas M. bovis induced the expression of proteins involved in fibrin formation, IDV co-infection counteracted this coagulation mechanism and downregulated other acute-phase response proteins, such as complement component 4 (C4) and plasminogen (PLG)." (PMID 38543727, 2024).
cognitive decline (2 papers, 2019 to 2021). "Patients with higher levels of plasma fibrinogen and plasminogen modulating neuroinflammation had worsening cognitive decline and Aβ deposition." (PMID 33514370, 2021).
coronary artery stenosis (2 papers, 2018 to 2020). "Thus, it is possible that Lp(a) competes with plasminogen and interferes with fibrinolysis, thereby promoting thrombosis and coronary artery stenosis." (PMID 29769559, 2018).
coronary atherosclerosis (2 papers, 2016 to 2024). Atherosclerosis of the coronary vasculature. "Interestingly, PLG, ITIH4, FN1, and ANGPTL4, all protective against MI, were also inferred to be protective against coronary atherosclerosis." (PMID 40027362, 2024).
empyema (2 papers, 2021 to 2023). An accumulation of pus in a body cavity, usually the pleural space. "Plasminogen accumulates in the pleural fluid of patients with empyema due to inhibited plasminogen activation." (PMID 35126140, 2021). "Plasminogen activator inhibitor 1 (PAI-1) is overexpressed in pleural fluids in empyema by up to three orders of magnitude, and is the most effective mechanism-based inhibitor (serpin) of tissue (tPA) and urokinase (uPA) plasminogen activators —therapeutics used for IPFT." (PMID 37242740, 2023).
endometrial carcinoma (2 papers, 2022 to 2024). A malignant tumor arising from the epithelium that lines the cavity of the uterine body. "The level of plasminogen, known as a TA target, increased in endometrial cancer and was further increased by TA treatment." (PMID 35371322, 2022). "Plasminogen, plasmin and tPA levels in the uterus and plasma were increased in the endometrial cancer group." (PMID 35371322, 2022). "The results of our study indicate that TA ameliorated the endometrial cancer induced by MNU and estradiol by regulating the macrophage/MMP-12/plasminogen/angiostatin signal transmission pathway." (PMID 35371322, 2022).
epilepsy (2 papers, 2025). A brain disorder characterized by episodes of abnormally increased neuronal discharge resulting in transient episodes of sensory or motor neurological dysfunction, or psychic dysfunction. "The growing body of evidence suggests that the plasminogen activation (PA) system plays a significant role in a number of neurologic disorders, including epilepsy." (PMID 41154178, 2025). "Background/Objectives: Growing evidence implicates that processes mediated by cytokines, growth factors, and the plasminogen activation (PA) system play crucial roles in the pathogenesis of epilepsy and its comorbidities." (PMID 41154178, 2025).
hepatocellular carcinoma (2 papers, 2011 to 2023). A malignant tumor that arises from hepatocytes. "PLG was over-expressed in HBV positive hepatocellular carcinoma tissues and cells." (PMID 37006234, 2023). "We thus identified SPARC, PLG, G6PC, NR1D2 and AGRP as RORα targets in hepatoma cells." (PMID 21818335, 2011).
Hydrocephalus (2 papers, 2024 to 2025). Hydrocephalus is an active distension of the ventricular system of the brain resulting from inadequate passage of CSF from its point of production within the cerebral ventricles to its point of absorption into the systemic circulation. "Interestingly, plasminogen deficiency has also been shown to cause obstructive hydrocephalus and Dandy–Walker malformation, suggesting that loss of PLAT causes these defects by disrupting plasmin production." (PMID 39574431, 2024). "It remains unclear whether the pathogenesis of DWM associated with the loss of PLAT and PLG involves the same mechanism underlying the development of hydrocephalus." (PMID 39574431, 2024).
infarction (2 papers, 2008 to 2011). A localised pathological necrosis of tissue resulting from obstruction of the blood supply usually by a thrombus, an embolus, or vascular torsion. "Genetic differences that alter the coagulative function of plasminogen may also influence disease pathogenesis by promoting pulmonary hemorrhage and infarction." (PMID 18566672, 2008).
injury (2 papers, 2017 to 2024). Damage inflicted on the body as the direct or indirect result of an external force, with or without disruption of structural continuity. "These distinct responses to plasminogen raise the possibility that chronic low levels of plasma leakage are fibrotic, whereas high levels of plasma leakage associated with extensive acute lung injury may serve to limit fibrogenesis." (PMID 28139758, 2017). "Liver injury itself can lead to DIC through decreased levels of fibrinogen, plasminogen and vitamin K-dependent coagulation factors." (PMID 39180107, 2024).
ischemia (2 papers, 2020 to 2025). A hypoperfusion of the BLOOD through an organ or tissue caused by a PATHOLOGIC CONSTRICTION or obstruction of its BLOOD VESSELS, or an absence of BLOOD CIRCULATION. "The plasminogen activation system is known to respond rapidly to brain injury, including ischemia, trauma, and seizures." (PMID 41154178, 2025).
Lupus (2 papers, 2012 to 2025). "While our data found a classical engagement of C3 with C3 and C4, nidogen-1 (NID1), and plasminogen (PLG), C3-LHF1 also engaged with other lupus- and autoimmune-related proteins, such as WDR1, RPL22, and PXDN, supporting its mechanism of interacting with surface binders." (PMID 41145914, 2025).
Lyme disease (2 papers, 2009 to 2014). Lyme disease (named after the towns in the USA where the disease was first identified) is a bacterial infection caused by Borrelia burgdorferi. "The finding that in accordance to the related Lyme disease spirochetes, B. recurrentis bind PLG and can disseminate from the blood to many distant organs, including the brain, supports the assumption that similar mechanisms could be involved." (PMID 19308255, 2009).
malaria (2 papers, 2016 to 2022). Malaria is a serious and sometimes fatal disease caused by a parasite that commonly infects a certain type of mosquito which feeds on humans. "In this study, we report the engineering of transgenic Anopheles mosquitoes that constitutively express human PAI-1 (huPAI-1) in the midgut and/or salivary glands in order to target plasminogen activation at the surface of the malaria parasite." (PMID 35618711, 2022). "Again, Fibrinogen beta chain and plasminogen released in the malaria plasma MPs were significantly higher compared to control plasma." (PMID 28352210, 2016). "In malaria, surface enolase assists in parasite invasion by binding to plasminogen." (PMID 28352210, 2016).
Methylmalonic aciduria (2 papers, 2018 to 2023). Increased concentration of methylmalonic acid in the urine. "Comprehensive re-testing confirmed the previous results and excluded mutations of diacylglycerol kinase-epsilon (DGKE), plasminogen (PLG) and methylmalonic aciduria and homocystinuria, cblC complementation type (MMACHC), but identified a homozygous deletion of CFHR3/1." (PMID 29728803, 2018).
migraine (2 papers, 2023 to 2024). "However, the associations between SERPING1 and BRH (PP.H4.abf = 0.47), ARHGAP25 and VD (PP.H4.abf = 0.34), PLG and any migraine (PP.H4.abf = 0.30), as well as ISOC1 and VD (PP.H4.abf = 0.06), did not receive sufficient support from co‐localization analysis, with a PP.H4.abf value below 0.5." (PMID 38898596, 2024). "We further found drugs targeted for another six proteins (CSK, FER, GP1BA, PLCG1, PLG, and SERPING1), although currently there are no indications for migraine." (PMID 38898596, 2024).
myopia (2 papers, 2021 to 2025). "Plasminogen (PLG) expression in the aqueous humor was significantly upregulated, suggesting that this protein may be involved in axial elongation and the pathogenesis of myopia by regulating collagen degradation." (PMID 41191163, 2025).
osteoporosis (2 papers, 2016 to 2021). A condition of reduced bone mass, with decreased cortical thickness and a decrease in the number and size of the trabeculae of cancellous bone (but normal chemical composition), resulting in increased fracture incidence. "Corroborating these findings, prior work from our group demonstrated that mice deficient in plasminogen, the principal protease that removes fibrin, suffer from persistent fibrin deposition within the skeleton and inflammation-driven systemic osteoporosis." (PMID 34938785, 2021). "Mice engineered to have a genetic deficit in the key fibrinolytic protease, plasmin, (PLG−/− mice) developed severe osteoporosis." (PMID 27773962, 2016).
osteosarcoma (2 papers, 2011 to 2022). A usually aggressive malignant bone-forming mesenchymal neoplasm, predominantly affecting adolescents and young adults. "Based on the available literature, the two parts (plasma fibrinogen (PF) and D-dimer) of the plasminogen-plasmin and coagulation system may be related to prognosis in osteosarcoma." (PMID 35463340, 2022).
pancreatitis (2 papers, 2018 to 2025). Inflammation of the pancreas. "Nonetheless, we found three markers, FN, Col4, and PLG, significantly different in PDAC versus pancreatitis." (PMID 29941541, 2018). "The pancreatitis activity score system(PASS) score, platelet(PLT) count, von Willebrand factor antigen(vWF:Ag), prothrombin time(PT), activated partial prothrombin time, fibrinogen, thrombin time, antithrombin III(ATIII), plasminogen, serum calcium(Ca) and D-dimer(D-D) were compared." (PMID 41394373, 2025).
pneumonia (2 papers, 2020 to 2022). An acute, acute and chronic, or chronic inflammation focally or diffusely affecting the lung parenchyma, caused by an infection in one or both of the lungs (by bacteria, viruses, fungi, or mycoplasma.). "Due to the limited effect of SAK on plasminogen in mice, we speculate that promoting fibrinolysis and evading host innate immunity may not be the main mechanism of SAK aggravating pneumonia in ST398-infected mice." (PMID 35739262, 2022).
preeclampsia (2 papers, 2023 to 2025). Preeclampsia is a hypertensive disorder of pregnancy that is characterized by new-onset hypertension with proteinuria presenting after 20 weeks of gestation, and depending on mild or severe forms may initially present with severe headache, visual disturbances, and hyperreflexia. "Preeclampsia is associated with defects in t-PA induced activation of plasminogen." (PMID 40703703, 2025). "D-dimer increased and plasminogen/plasmin inhibitor and fibrin clot lysability time decreased in preeclampsia." (PMID 40703703, 2025). "An increased expression of angiotensin receptor type-1, activated by plasminogen, impacts preeclampsia, leading to intermediate actions and reduced plasmin synthesis." (PMID 37987269, 2023).
Pulmonary hemorrhage (2 papers, 2008 to 2025). Pulmonary hemorrhage is a bleeding within the lungs. "In the lungs, ECSCR, KNG1, PLG, and transient receptor potential (TRP) cation channel subfamily C member 7 (TRPC7) were identified as factors that may contribute to pulmonary hemorrhage through various signaling pathways." (PMID 39764561, 2025).
radiation dermatitis (2 papers, 2018 to 2024). "We found that the development of radiodermatitis in mice is initiated by the accumulation of plasminogen in the irradiated skin where it is activated to plasmin." (PMID 30323258, 2018). "In summary, the data suggest that the development of radiodermatitis is strongly related to plasminogen levels." (PMID 30323258, 2018). "Here, we provide compelling evidence indicating that plasminogen is a critical factor in the development of radiodermatitis." (PMID 30323258, 2018). "In this work, we show with several lines of evidence that plasminogen, a pro-inflammatory factor, is key for the development of radiodermatitis." (PMID 30323258, 2018). "Taken together, these data strongly suggest that plasmin, the active form of plasminogen, is responsible for inducing key factors that are involved in the development of radiodermatitis." (PMID 30323258, 2018). "Taken together, our data show that the inhibition of plasminogen activation during and immediately after radiotherapy might be a potential treatment strategy to protect cancer patients from radiodermatitis and possible other tissue damage." (PMID 30323258, 2018). "However, plasminogen-deficient (plg−/−) mice and mice lacking plasminogen activators were mostly resistant to radiodermatitis." (PMID 30323258, 2018). "Our study has for the first time linked plasminogen activation to TGF-β expression, suggesting that inhibition of plasminogen might be an upstream event that can be used to suppress TGF-β activation for the prevention of radiodermatitis." (PMID 30323258, 2018). "Our study also for the first time links plasminogen activation to TGF-β expression in vivo, suggesting that inhibition of plasminogen can be used to suppress TGF-β activation for the prevention of radiodermatitis." (PMID 30323258, 2018). "Moreover, treatment with an inhibitor of plasminogen activation (tranexamic acid (TXA)) significantly delays the onset and decreases the severity of radiodermatitis in plg+/+ mice and completely prevents radiodermatitis in plg+/− mice." (PMID 30323258, 2018). "Finally, we found that genetic ablation of plasminogen or PAs prevents the formation of radiodermatitis in mice and that the inhibition of plasminogen activation by TXA significantly decreases the severity of radiodermatitis in plg+/+ mice and prevents radiodermatitis in plg+/− mice." (PMID 30323258, 2018). "Because the TXA treatment ended on day 10, the plasminogen level in TXA-treated mice began to slowly increase on day 16 post irradiation, but this increase did not seem to be sufficient to induce radiodermatitis." (PMID 30323258, 2018). "In sharp contrast, no increase in TGF-β expression was detected in the irradiated skin of plg−/− mice, showing that in the absence of plasminogen TGF-β was not induced and thus could not initiate the inflammation that is required for radiodermatitis to develop." (PMID 30323258, 2018).
relapsing fever (2 papers, 2009). Relapsing fever is an infection caused by bacteria of the genus Borrelia, excluding those responsible for Lyme disease belonging to the Borrelia burgdorferi complex. "Indeed, for thespirochetal causative agent of relapsing fever, using plasminogen knock-out mice, ithas been clearly shown that plasminogen is required for dissemination of thespirochete to the heart and brain in vivo." (PMID 19461880, 2009). "In summary, this is the first study showing the simultaneous and non-competitive binding of CFH and PLG to the outer surface protein HcpA of B. recurrentis, the agent of louse-borne relapsing fever." (PMID 19308255, 2009).
respiratory distress syndrome (2 papers, 2018). "In the 1970s, plasminogen administration was used for very premature infants with respiratory distress syndrome because of its fibrinolytic effect." (PMID 29304073, 2018).
scrapie (2 papers, 2007 to 2014). A fatal disease of the nervous system in sheep and goats, characterized by pruritus, debility, and locomotor incoordination. "Plasminogen, immobilized to beads, was used as a capturing tool for PrPSc in brain homogenates from scrapie affected sheep and the binding reaction was monitored in real-time in an ultrasonic cell." (PMID 17659071, 2007). "The specificity of the interaction of plasminogen to PrPSc was demonstrated on scrapie PK-untreated and PK-treated samples and confirmed on healthy brain samples." (PMID 17659071, 2007). "By contrast, in PK untreated scrapie affected samples, there is good evidence that PrPSc is bound to plasminogen." (PMID 17659071, 2007). "In contrast, challenge of plasminogen-deficient mice (Plg−/−) intraperitoneally with RML scrapie prions showed no major effect of plasminogen on survival, although levels of PrPSc were higher in wild-type mice at the onset of disease symptoms." (PMID 24833721, 2014). "Thus, it was only in the scrapie affected tissues that there evidence of a significant reaction and these results argue for an interaction between the plasminogen coated beads and PrPSc but not between the plasminogen coated beads and PrPc or any non-PrP component of the sample." (PMID 17659071, 2007). "Thus, the aim of this study was to investigate the interactions between plasminogen coated beads and PrPSc in scrapie affected brain tissue, particularly in the absence of a proteinase K pre-digestion step, with a view to exploring its potential for use as a sensitive detection system for PrPSc." (PMID 17659071, 2007).